VRK1 (VRK serine/threonine kinase 1)
Diseases named in the same sentence as VRK1 in open-access papers (continued):
Sharing a sentence is not in itself a finding about the gene and the disease.
neuroblastoma (5 papers, 2015 to 2025). Neuroblastoma (NB) is the most common solid, extracranial childhood tumor. "Our gene expression and ontology analysis predicts that VRK1 expression is associated in neuroblastoma tumors with signaling pathways involved in cell cycle regulation, DNA replication or DNA repair." (PMID 33233777, 2020). "We demonstrate that VRK1 is highly expressed in high-grade neuroblastoma and is associated with proliferation and dedifferentiation in tumor cells." (PMID 33233777, 2020). "The study identified VRK1 as a novel neuroblastoma tumor progression marker that regulates cell proliferation." (PMID 38157278, 2023). "VRK1 KO resulted in a significant decrease in cell fitness approximately 8 days following viral transduction in neuroblastoma NB-1 cells, as well as in a larger panel of NB and GBM cell models." (PMID 36040810, 2022). "We have previously seen that VRK1 expression strongly correlates with aggressiveness in neuroblastoma tumors." (PMID 33233777, 2020). "We decided to further explore the connection between MYCN transcription factor and VRK1 in neuroblastoma." (PMID 33233777, 2020). "We finally analyzed VRK1 protein levels in a panel of commonly used neuroblastoma cell lines and primary PDX-derived cells." (PMID 33233777, 2020). "Neuroblastoma cells were treated with siRNA against VRK1 or with control siRNA before xenograft transplantation on recipient immunocompromised mice." (PMID 33233777, 2020). "This indicates that, despite the possible relationship between VRK1 and MYCN, VRK1 expression strongly correlates with neuroblastoma unfavorable prognosis and aggressiveness independently of the MYCN amplification status." (PMID 33233777, 2020). "Our work suggests that VRK1 synergize with MYCN to drive NB progression and that VRK1 inhibition may constitute a novel cell-cycle-targeted strategy for anticancer therapy in neuroblastoma." (PMID 33233777, 2020). "Our study also suggests that VRK1 inhibition may constitute a novel cell-cycle-targeted strategy for anticancer therapy in neuroblastoma." (PMID 33233777, 2020). "Functional experiments show that VRK1 is essential for NB cell proliferation and tumor progression, and thus could be a new target for neuroblastoma treatment." (PMID 33233777, 2020). "Given the association of VRK1 with malignancy, we investigated whether VRK1 depletion on neuroblastoma cells would impact tumor progression." (PMID 33233777, 2020). "Therefore, we used transient siRNA transfection to partially reduce the expression of VRK1 in neuroblastoma cells and study the functional consequences." (PMID 33233777, 2020). "The possible implication of VRK1 in neuroblastoma or other pediatric cancers is unknown." (PMID 33233777, 2020). "Given the evidence linking VRK1 to tumor progression and the connection with MYCN, we decided to analyze the contribution of this protein to neuroblastoma cell biology, focusing on its pathological significance and prognostic value." (PMID 33233777, 2020). "In neuroblastoma PDX tissues, all MYCN-positive cells showed expression of VRK1." (PMID 33233777, 2020). "MYCN-amplified neuroblastoma cell lines are more sensitive to VRK1 inhibition than cells with no MYCN amplification, reinforcing this possibility." (PMID 33233777, 2020). "VRK1 expression is also significantly higher in MYCN-amplified versus nonamplified neuroblastoma tumors." (PMID 33233777, 2020). "Amplification of MYCN in neuroblastoma tumors correlates with high VRK1 gene expression and aggressiveness, although the levels of VRK1 do not correlate with the levels of MYCN expression in nonamplified tumors." (PMID 33233777, 2020). "In addition to mRNA expression, VRK1 protein detection by immunohistochemistry on our own collection of 36 human neuroblastoma tumor samples shows high VRK1 expression in M stage tumors and patient-derived xenografts (PDXs) derived from high-grade NB patients, compared to L1 tumors." (PMID 33233777, 2020).
neuroblastoma (continued). "VRK1 is highly expressed in the International Neuroblastoma Staging System (INSS) stage 4 NB compared with normal adrenal tissue, and significant differences can be observed between more aggressive neuroblastoma stages (stages 3 and 4) and more benign ones (Stages 1, 2 and 4S)." (PMID 33233777, 2020). "Therefore, we determined if VRK1 knock-down could affect the organization of CBs in three cell lines, HeLa, MCF7 and neuroblastoma SH-SY5Y cells." (PMID 26068304, 2015). "VRK1 expression was variable among the cell lines and does not seem to correlate with MYCN amplification, but the kinase was expressed in all neuroblastoma cell lines and PDX samples tested." (PMID 33233777, 2020).
astrocytomas (3 papers, 2013 to 2022). "Also VRK1 is expressed at high levels, correlating with Ki67 and p63 in non-small lung cancer and high-grade astrocytomas." (PMID 24731990, 2014). "High-grade astrocytomas overexpress high VRK1 and VRK2 RNA and protein levels (this work)." (PMID 24079673, 2013). "VRK1 and VRK2 (Vaccinia-related kinase-1, -2) expression, as well as proliferation markers, were determined in a tissue microarray containing 105 primary astrocytoma biopsies." (PMID 24079673, 2013). "The expression of VRK1 and VRK2 proteins was determined in 105 astrocytomas." (PMID 24079673, 2013). "VRK1 expression only correlated with p63 expression in both low and high-grade astrocytomas, while VRK2 expression correlated with ki67 levels only in high-grade astrocytomas." (PMID 24079673, 2013). "However, none of these alterations were related to VRK1 or VRK2 expression in astrocytomas, suggesting that these proteins could be involved in astrocytoma pathogenesis by different mechanisms." (PMID 24079673, 2013).
Ewing sarcoma (3 papers, 2009 to 2025). A small round cell tumor that lacks morphologic, immunohistochemical, and electron microscopic evidence of neuroectodermal differentiation. "Further, while our data showed a robust connection between VRK2 expression and VRK1 dependency, some tumor lineages, like Ewing sarcoma, demonstrated high VRK2 expression and a strong dependency on VRK1, suggesting that VRK1 may also be required for other tumor cell functions in particular contexts." (PMID 36040810, 2022). "While genes such as BCL11B and VRK1 are well characterized, others, such as IGF2BP1 and LSM6, remain poorly studied, yet they may offer valuable insights into the biology and vulnerabilities of Ewing sarcoma." (PMID 41444391, 2025).
lung squamous cell carcinomas (3 papers, 2008 to 2023).
myeloma (3 papers, 2020 to 2024). "VRK1 has been described as a proliferation control protein in human fibroblasts and in some cancers like head and neck or myeloma." (PMID 33233777, 2020). "Previously, it was shown that VRK1 expression could promote cell proliferation in myeloma by regulating cell cycle-related proteins." (PMID 37547297, 2023).
pontocerebellar hypoplasia type 1A (3 papers, 2018 to 2025). Any non-syndromic pontocerebellar hypoplasia in which the cause of the disease is a mutation in the VRK1 gene. "Pontocerebellar hypoplasia type 1A (PCH1A) is caused by a homozygous mutation in the VRK1 gene (602168)." (PMID 40182349, 2025). "Strikingly, the proband suffered from congenital arthrogryposis, which is not a common feature related to ataxias, although it is for instance, associated with pontocerebellar hypoplasia type 1A due to VRK1 mutations that occasionally includes ataxia." (PMID 38003592, 2023).
Ataxia (2 papers, 2023 to 2024). Ataxia refers to impaired coordination of voluntary muscle movement. "PCH1A is a result of a mutation in the Vaccinia related kinase 1 (VRK1) locus with clinical manifestations of psychomotor retardation, hypotonia, ataxia, poor feeding, and respiratory insufficiency." (PMID 38347586, 2024).
bladder cancer (2 papers, 2022 to 2023). "In order to further determine the risk factors associated with OS in patients with bladder cancer, we conducted univariate and multivariate analysis to confirm whether VRK1 is an independent risk factor for poor prognosis." (PMID 35559251, 2022). "The results suggested: compared with the blank control group (shVRK1-NC), shVRK1-1 and shVRK1-2 can significantly knockdown the expression level of VRK1 in bladder cancer cells after transfection, and shVRK1-2 has a higher knockdown efficiency." (PMID 35559251, 2022). "By comparing the weight of tumor-bearing tissues, we found that VRK1 knockdown can significantly inhibit the proliferation of bladder cancer cells in the body." (PMID 35559251, 2022). "We verified the bladder cancer tissue of the patients we included in the study by reverse transcription qPCR, and found that the expression of VRK1 in cancer tissues was significantly higher than that in paracancerous tissues." (PMID 35559251, 2022). "These mature research studies also provide better help for follow-up research on the role of VRK1 in bladder cancer." (PMID 35559251, 2022). "In this study, we first screened the differential genes of bladder cancer from GEO and TCGA data, and screened the differentially expressed molecules VRK1 from the differential genes." (PMID 35559251, 2022). "This study found a new potential treatment target: vaccinia-related kinase 1 (VRK1) and explored the function and mechanism of VRK1 in the development of bladder cancer." (PMID 35559251, 2022). "This also provides some reference for our follow-up experiments to explore the role of VRK1 in the tumorigenesis and development of bladder cancer." (PMID 35559251, 2022). "qRT-PCR was used to detect the expression level of VRK1 in 5 bladder cancer cell lines (J82, SW780, T24, 5637, and UM-UC-3) and a normal human bladder normal epithelial cell (SV-HUC-1)." (PMID 35559251, 2022). "The results of fluorescence qPCR and Western blot showed that the expression levels of VRK1 in various bladder cancer cell lines are quite different, with the highest expression levels in T24 and 5637 cells, followed by UM-UC-3, J82, and SW780 cells." (PMID 35559251, 2022). "In order to better study the possible mechanism of VRK1 in the biology of bladder cancer, we conducted in vivo experiments." (PMID 35559251, 2022). "All research results consistently reflect the positive relationship between low VRK1 expression and better prognosis of bladder cancer." (PMID 35559251, 2022). "The results manifest that compared with the blank control group (shVRK1-NC), knocking down VRK1-2 can significantly inhibit the growth of bladder cancer cell T24 in vivo." (PMID 35559251, 2022). "In summary, VRK1 expression is significantly related to the staging, grade, and poor prognosis of patients with bladder cancer." (PMID 35559251, 2022). "The immunohistochemistry results also confirmed that VRK1 is highly expressed in bladder cancer tissues and mainly expressed in the nucleus." (PMID 35559251, 2022). "The results of in vitro cytology experiments all show that VRK1 exhibits a kind of “oncogene” performance in bladder cancer cell lines." (PMID 35559251, 2022). "In the analysis of clinical data, among 101 bladder cancer patients included, 43 cases (42.6%) were in the VRK1 low expression group, and 58 cases (57.4%) were in the VRK1 high expression group." (PMID 35559251, 2022). "In order to further study the effect of knocking down VRK1 on the proliferation of bladder cancer cells in vivo, the shVRK1-NC and shVRK1-2 bladder cancer T24 cells transfected with lentivirus were collected, and then injected into nude mice under the skin." (PMID 35559251, 2022). "This also provides some reference for our follow-up experiments to explore the role of VRK1 in the biological process of the tumorigenesis and development of bladder cancer." (PMID 35559251, 2022).
bladder cancer (continued). "First, TCGA database and tissue microarray analysis showed that VRK1 was significantly upregulated in bladder cancer." (PMID 35559251, 2022). "In vivo, nude mice transplanted tumors further prove that low VRK1 can significantly inhibit the proliferation capacity of bladder cancer cells." (PMID 35559251, 2022). "At the same time, in vivo and in vitro experiments have shown that downregulation of VRK1 can significantly inhibit the proliferation of bladder cancer cells." (PMID 35559251, 2022). "In vivo experimental results also indicate that VRK1 has the expression status of “oncogenes” in the bladder cancer tissue." (PMID 35559251, 2022). "Among the 101 bladder cancer patients included, 43 cases (42.6%) were in the VRK1 low expression group, and 58 cases (57.4%) were in the VRK1 high expression group." (PMID 35559251, 2022). "Then, we verified from the cytology and the nude mouse level that the reduction of VRK1 expression can inhibit the proliferation and invasion of bladder cancer cells." (PMID 35559251, 2022). "In order to further study the role of VRK1 in the invasion and migration of bladder cancer cells, Transwell was used to detect the invasion and migration ability of T24 and 5637 cells after knocking down VRK1." (PMID 35559251, 2022). "At the cytological level, we first used qRT-PCR to detect the expression level of VRK1 in five bladder cancer cell lines (J82, SW780, T24, 5637, and UM-UC-3) and a normal human bladder normal epithelial cell (SV-HUC- 1)." (PMID 35559251, 2022). "We tried to find out whether the expression of VRK1 is related to the immune infiltration of bladder cancer." (PMID 35559251, 2022). "Our analysis of health information and clinical data have reflected that the high expression of VRK1 is related to the poor prognosis of patients with bladder cancer, which has also aroused our interest in further research and exploration at the level of cytology and nude mice." (PMID 35559251, 2022). "In addition, our research hopes to further explore the specific biological functions of VRK1 in bladder cancer through in vivo and in vitro experiments." (PMID 35559251, 2022). "In addition, cell functional studies have shown that VRK1 can significantly inhibit the proliferation, migration, and invasiveness of bladder cancer cells." (PMID 35559251, 2022). "Moreover, VRK1 was low expressed in 43 bladder cancer tissue samples (42.6%), and highly expressed in 58 bladder cancer tissue samples (57.4%)." (PMID 35559251, 2022). "Therefore, the purpose of this study is to evaluate the role of VRK1 in the prognosis of bladder cancer." (PMID 35559251, 2022). "Therefore, the expression of VRK1 may also have a certain relationship with the immune infiltration of bladder cancer." (PMID 35559251, 2022). "However, there is no relevant research on VRK1 and bladder cancer." (PMID 35559251, 2022).
colorectal cancer (2 papers, 2019 to 2025). A primary or metastatic malignant neoplasm that affects the colon or rectum. "Knocking down VRK1 in HT-29 and HCT-116 colorectal cancer cell lines led to reduced BANF1 protein levels, which was associated with inhibited cell proliferation and migration." (PMID 40384864, 2025). "In particular, we identified a small set of genes (in particular VRK1, CSNK1A1, and PIK3R4) that were more dramatically depleted in colorectal cancer cell lines, than a range of leukemia, liver and pancreatic cancer cell lines." (PMID 31891587, 2019).
motor neuron degeneration (2 papers, 2021 to 2025). "PCH variants associated with motor neuron degeneration have been reported with variants of all genes associated with PCH1 (VRK1, EXOSC3/EXOSC8/EXOSC9, SLC2A46)." (PMID 40428407, 2025).
oral cancer (2 papers, 2022 to 2025). "Hub genes VRK1, NUP37, HMMR, SPC25, and RUVBL1 were identified to be related to oral cancer at both molecular level and clinical levels." (PMID 36052378, 2022).
osteosarcoma (2 papers, 2021 to 2023). A usually aggressive malignant bone-forming mesenchymal neoplasm, predominantly affecting adolescents and young adults. "First, we treated osteosarcoma cells with RNase R and the transcripts level of circVRK1 and VRK1 mRNA were tested with qRT-PCR." (PMID 34424826, 2021). "Moreover, RNA stability assay was performed to compare the stability of circular isoform and linear isoform of VRK1 in osteosarcoma cells, and the results illustrated that circVRK1 was more stable than VRK1 mRNA." (PMID 34424826, 2021).
viral infection (2 papers, 2021 to 2022). "By 7 h postinfection (hpi), wild-type (WT) virus infection shifted VRK1 from highly soluble in uninfected cells to a more insoluble state." (PMID 35543552, 2022). "Interestingly, many of the candidate proteins have only limited functional links to viral infection and immune regulation and were not previously known to interact with NAs (e.g., c8orf88, DTYMK, KIF2A, PDAP1, PDIA5, TAOK1, TAOK2, and VRK1)." (PMID 34853303, 2021).
adenoma (1 paper, 2025). A neoplasm arising from the epithelium. "For instance, VRK1 showed a consistent upregulation in tumor/adenoma tissue with respect to adjacent mucosa, while WDR78, LPAR1, and RELL1 (the top three downregulated circRNA host genes in our dataset) decreased." (PMID 39980011, 2025).
allergic disease (1 paper, 2023). An immune response that occurs following re-exposure to an innocuous antigen, and that requires the presence of existing antibodies against that antigen. "Alteration in epigenetic patterns have also been associated with allergic diseases, in which the role of VRK1 has not been studied." (PMID 37179361, 2023).
benign breast neoplasms (1 paper, 2018). "VRK1 was only in the top 25% of upregulated genes in ductal breast carcinoma in situ or mucinous breast carcinoma (respectively), and showed no significant upregulation in benign breast neoplasms." (PMID 30180179, 2018).
brain tumors (1 paper, 2022). "In brain tumors, lacking VRK1, this compensatory mechanism is impaired by silencing the VRK2 gene, and thus no VRK2 isoform can partially replace VRK1, and cells become more sensitive to DNA damage." (PMID 36011043, 2022).
cardiomyopathies (1 paper, 2021). "The patient was a heterozygous carrier of VUS in DNA methyltransferase 1 (DNMT1) gene (c.1043C> T), and VRK serine/threonine kinase 1 (VRK1) gene (c.8G>A), in addition to dynamin 2 (DNM2) gene (c.2576_2578delCCA), which is associated with severe cardiomyopathies." (PMID 33567613, 2021).
cerebral infarction (1 paper, 2023). An ischemic condition of the brain, producing a persistent focal neurological deficit in the area of distribution of the cerebral arteries. "Therefore, Circ VRK1 siRNA intervention might reduce the incidence of cerebral infarction." (PMID 36707796, 2023).